ITGBL1 (integrin subunit beta like 1)
Diseases named in the same sentence as ITGBL1 in open-access papers (continued):
Sharing a sentence is not in itself a finding about the gene and the disease.
gastric cancer (5 papers, 2022 to 2025). A primary or metastatic malignant neoplasm involving the stomach. "shown that the levels of RNA and protein of ITGBL1 were elevated in samples from patients with gastric cancer when compared to the neighbouring non‐tumour tissues." (PMID 38332530, 2024). "Meanwhile, ITGBL1 promotes the proliferation of gastric cancer cells through activating the Akt pathway, which is also a positive regulatory pathway to promote the malignant progression of PC." (PMID 35584452, 2022). "The function of ITGBL1 in gastric cancer was also investigated and the conclusion was that ITGBL1 is a potential predictor by promoting the migration and invasion of gastric cancer cells." (PMID 35584452, 2022). "However, the information on the involvement of ITGBL1 in gastric carcinoma (GC) is limited." (PMID 35596183, 2022). "Our analysis revealed dynamic remodeling of the tumor microenvironment during gastric cancer progression, characterized by the expansion of dysfunctional CD8+ T cells, pro-tumorigenic fibroblasts (e.g., ITGBL1+, PI16+, and ITLN1+), and altered myeloid populations." (PMID 41246350, 2025).
non-small cell lung carcinoma (4 papers, 2018 to 2022). A group of at least three distinct histological types of lung cancer, including non-small cell squamous cell carcinoma, adenocarcinoma, and large cell carcinoma. "In contrast, ITGBL1 expression was downregulated in non-small cell lung cancer (NSCLC) and inhibited migration and invasion via binding to miR-576-5p." (PMID 35596183, 2022).
chronic hepatitis B (2 papers, 2024 to 2025). "In individuals with chronic hepatitis B, ITGBL1, which promotes cell migration, has been shown to regulate fibrogenesis and is part of a six-gene signature predictive of cirrhosis." (PMID 38565287, 2024).
Cirrhosis (2 papers, 2023 to 2024). A chronic disorder of the liver in which liver tissue becomes scarred and is partially replaced by regenerative nodules and fibrotic tissue resulting in loss of liver function. "Moreover, ITGBL1, LOXL1 and PPP4R1 are all significantly enriched in the Ribosome pathway, so these three genes may also influence the formation of cirrhosis by regulating ribosome function." (PMID 37808522, 2023).
leukemia (2 papers, 2020 to 2022). A malignant (clonal) hematologic disorder, involving hematopoietic stem cells and characterized by the presence of primitive or atypical myeloid or lymphoid cells in the bone marrow and the blood. "For example, in acute myeloid leukemia (AML), ITGBL1 methylation was reported to impact prognosis, and patients with hypermethylation of ITGBL1 tended to have leukemia-free survival and shorter OS." (PMID 35596183, 2022).
metastatic cancer (2 papers, 2020 to 2021). A carcinoma which has spread from the original site of growth to another anatomic site. "Similarly, the experimental liver metastasis model also demonstrated the promoting effect of metastatic cancer by ITGBL1-enriched EVs." (PMID 32139701, 2020).
metastatic tumors (2 papers, 2020 to 2023). "Through RNA-seq analyses, it was discovered that primary tumors release extracellular vesicles enriched with integrin subunit beta like 1, which facilitates the growth of distal metastatic tumors by creating a fibroblast-niche environment." (PMID 38087342, 2023). "Histological analysis demonstrated the promoting effect of conditioned medium from ITGBL1-overexpressing WI-38 or LX-2 on the growth of liver metastatic tumors." (PMID 32139701, 2020). "In vivo imaging analysis showed that purified ITGBL1-enriched EVs promoted the growth of lung metastatic tumors, whereas silencing ITGBL1 markedly decreased the metastatic growth." (PMID 32139701, 2020). "Targeting the EVs-ITGBL1-CAFs-TNFAIP3-NF-κB signaling axis provides an attractive approach for treating metastatic diseases." (PMID 32139701, 2020). "Interestingly, our preliminary study also showed that TGF-β in the EVs was not alerted in ITGBL1 overexpressing or silencing CRC cells, and their effect on TGF-β/Smads signaling pathway was little in the targeted HCT116 cells and CAFs from liver metastatic tumors." (PMID 32139701, 2020).
osteoarthritis (2 papers, 2021 to 2025). A noninflammatory degenerative joint disease occurring chiefly in older persons, characterized by degeneration of the articular cartilage, hypertrophy of bone at the margins and changes in the synovial membrane. "Upregulated gene predicted to be secreted proteins exclusive to 2′3′-cGAMP activation show efficacy in reducing osteoarthritis or enhancing cartilage formation (ITGBL1, Notum, serpinG1)." (PMID 40861855, 2025).
Ataxia (1 paper, 2020). Ataxia refers to impaired coordination of voluntary muscle movement. "A microdeletion (95kb) was associated with impaired gait, delayed motor and language development, low IQ and mild dysmorphism, whereas a larger deletion (202 kb), affecting partially both FGF14 and ITGBL1, was associated with ataxia exacerbated by fever, but with normal IQ." (PMID 32112487, 2020). "Nine patients had ataxia, and all affected patients harboured an interstitial deletion of chromosome 13q33.1 encompassing the entire FGF14 and integrin subunit beta like 1 (ITGBL1) genes." (PMID 32112487, 2020).
bone metastasis (1 paper, 2022). Transfer of a neoplasm from its primary site to bones. "In the validation dataset of GSE14020, GJA1, IGFBP6, ITGBL1, SLC44A1, and TGFBI expressions in the bone-metastasis group were different from those in the control group." (PMID 36046013, 2022).
Cognitive impairment (1 paper, 2025). Abnormal cognition is characterized by deficits in thinking, reasoning, or remembering. "However, exceptions were reported, where a 200 kbp deletion spanning FGF14 exons 2–5 and ITGBL1 gene and a 168 kbp deletion spanning FGF14 exons 4–5 and ITGBL1 gene, respectively, did not cause cognitive impairment." (PMID 41099962, 2025).
colorectal adenocarcinoma (1 paper, 2025). The most common type of colorectal carcinoma. "Additionally, RBM15 regulates m6A methylation to upregulate integrin subunit beta like 1 (ITGBL1) expression, promoting the progression of colorectal adenocarcinoma." (PMID 40370450, 2025).
endometriosis (1 paper, 2021). The growth of functional endometrial tissue in anatomic sites outside the uterine body. "Above all, ITGA7, ITGBL1 and SORBS1 may be associated with cell proliferation, invasion and migration of endometriosis, hsa-miR-6745 may be a potential miRNA biomarker, and its high expression may be associated with poor prognosis." (PMID 34409913, 2021). "Further research is needed to elucidate the role of this new target gene in endometriosis, and ITGA7, ITGBL1, SORBS1 and IGHM may be therapeutic target genes." (PMID 34409913, 2021).
gastric tumor (1 paper, 2025). "In GC, Integrin beta-like 1 (ITGBL1) via the Akt/Fibulin-2 axis (FBLN2) can enhance the metastatic capacity of the gastric tumor cell by determining AR." (PMID 40664635, 2025).
keloid (1 paper, 2025). An irregularly shaped, elevated mark on the skin caused by deposits of excessive amounts of collagen during wound healing. "Interestingly, human keloid-derived dermal fibroblasts constitutively expressed ITGBL1, suggesting that ITGBL1 could be involved in the exacerbation of scarring." (PMID 39558136, 2025).
metastasis (1 paper, 2020). The spread or migration of cancer cells from one part of the body (where they first appeared) to another. "In our present studies, we have found that integrin beta-like 1 (ITGBL1) was enriched in the plasma EVs of CRC patients with lung and liver metastasis." (PMID 32139701, 2020).
prostate tumors (1 paper, 2017). "In this study, we demonstrated that 255 DEGs were up/down-regulated in prostate tumors compared with BPH tissues; qRT-PCR also confirmed that the DEGs such as ITGBL1, KRT15, TGM4, and HOXA7 genes were up/down-regulated in PCa tissue and cell lines." (PMID 29285211, 2017).
stomach adenocarcinoma (1 paper, 2022). "The change in unpaired data in the ITGBL1 transcription level in stomach adenocarcinoma tissues was 3.5-fold relative to that in unpaired normal tissues (P = 3.14e−11)." (PMID 35596183, 2022).
thyroid cancer (1 paper, 2025). "For instance, ITGBL1, an integrin subunit beta-like 1 protein, was not classified as a hub gene, but its overexpression was significantly associated with poor overall survival and advanced stages of thyroid cancer." (PMID 40458726, 2025).
cancer (24 papers, 2012 to 2025). A tumor composed of atypical neoplastic, often pleomorphic cells that invade other tissues. "Previous studies have reported that the increased expression of ITGBL1 is associated with tumorigenesis and poorer prognosis in a variety of cancers." (PMID 32537856, 2020). "Signaling pathway related to high ITGBL1 expression was mainly linked to cytoskeleton, Wnt signaling pathway, pathway in cancer, and pathway related to tumor development." (PMID 32211321, 2020). "Data showed that ITGBL1 was clearly increased in individual cancer stages, histologic subtypes, and nodal metastasis status of COAD." (PMID 39840822, 2025). "Many investigations have been conducted to examine the biological roles of ITGBL1 in numerous primary tumours and cancer cell lines." (PMID 38332530, 2024). "Previously, ITGBL1 was reported to promote metastasis in various types of cancers by controlling either Wnt-PCP signaling or the FAK/SRC or TGF-β signaling pathways." (PMID 35066808, 2022). "ITGBL1 is known to promote cancer metastasis and invasion by the WNT/PCP, FAK/SRC, and TGF-β signaling pathways, yet our previous study suggested that ITGBL1 was a secreted protein and that it inhibited integrin activation." (PMID 35066808, 2022). "Our group confirmed that the primary cancer releases ITGBL1 (integrin β1)-enriched EVs and promotes the growth of distal metastatic cancers through the formation of a fibroblast niche." (PMID 33722297, 2021). "Further studies will show if ITGBL1 can be exploited as a cancer biomarker and/or molecular target for experimental biological therapy." (PMID 32961775, 2020). "In an orthotopic CRC model by which cancer cells were implanted into the cucum, ITGBL1-enriched EVs also accelerated liver metastatic tumor growth." (PMID 32139701, 2020). "Previous studies also showed that ITGBL1 was involved in the development and progression of several cancers." (PMID 32537856, 2020). "Using immunedeficient mice, we demonstrate the ITGBL1-enriched EVs derived from highly metastatic cancer cells accelerate metastatic cancer growth through a CAF activation mechanism." (PMID 32139701, 2020). "The key function of cancer cell-derived ITGBL1-enriched EVs is involved in converting lung fibroblasts and hepatic stellate cells to an activated phenotype, such as myofibroblasts." (PMID 32139701, 2020). "Meanwhile, other cell-cell adhesion-related molecules, such as laminins (LAMA4, LAMA5, LAMB1, LAMB2 and LAMC2) and integrins (ITGA5, ITGA5, ITGB5, ITGA11 and ITGBL1), are elevated in cancer tissues." (PMID 22905095, 2012). "The TIMER database showed that ITGBL1 was highly expressed in many cancers, including COAD." (PMID 39840822, 2025). "ITGBL1 expression and clinical features in grastric cancer patient samples." (PMID 38332530, 2024). "Previous studies have indicated that ITGBL1 plays a key role in some types of cancer." (PMID 35584452, 2022). "Accumulating evidence indicated that ITGBL1 was crucial in carcinogenesis and cancer progression." (PMID 35596183, 2022). "Besides, ITGBL1 in GC tissues derived from TCGA samples was significantly highly expressed in subgroups including cancer stage, tumor grade, and lymph node metastasis compared with normal gastric tissues." (PMID 35596183, 2022). "Integrins, including TGA5, ITGA5, ITGB5, ITGA11, and ITGBL1 elevated in cancer tissues." (PMID 29843204, 2019). "Nonetheless, we believe preferential inhibition of trailing edge integrins by ITGBL1 is a novel mechanism explaining how integrin inhibition may promote cell migration during cancer cell invasion and metastasis, where ITGBL1 has been shown to be a key regulator." (PMID 35066808, 2022). "This may suggest that ITGBL1 function is cancer type-specific." (PMID 32961775, 2020).
cancer (continued). "Genes encoding for integrins (such as ITGAV, ITGBL1, and ITGB1) that can promote tumor cell proliferation and migration and genes related to the Hippo signaling pathway, one of the signaling pathways which has been implicated in cancer by promoting cell proliferation, were also downregulated." (PMID 32616706, 2020). "Integrin, beta-like 1 (ITGBL1) is a β-integrin-related extracellular matrix protein and is reported to promote progression of some types of cancer." (PMID 35584452, 2022). "Thus, ITGBL1 might be a key regulator linking stemness and immune response in cancers." (PMID 34975338, 2022). "Knowing that EVs secreted from cancer cells is an important communicator between primary tumors and distant metastasis, and crucial roles of CAFs in tumor metastasis and growth, we asked the question of whether ITGBL1-enriched EVs participate in the activation of fibroblasts." (PMID 32139701, 2020). "To determine the expression pattern of ITGBL1 in HCC tissues, the TCGA and Oncomine databases were searched, and we found that the ITGBL1 mRNA levels were significantly increased in HCC cancer tissues compared to the adjacent normal tissues." (PMID 32537856, 2020). "Recent studies have reported that integrin β like 1 protein (ITGBL1), which is also called the ten beta integrin EGF-like repeat domain, regulated various forms of cancer cell migration, invasion and metastasis through the WNT/PCP, FAK/SRC, and TGF-β signaling pathways." (PMID 35066808, 2022). "Recently, ITGBL1, as an ECM-related protein, has been found to be dysregulated in malignant tumors; however, the function and biological mechanism of ITGBL1 still remains unclear." (PMID 35596183, 2022). "Although emerging studies have unveiled the important roles of ITGBL1 in the invasion, migration and chemoresistance of malignant tumours, the roles of ITGBL1 in the development and progression of HCC are not clear." (PMID 32537856, 2020). "We determined whether ITGBL1 regulated the KRT17 expression through TGF‐β1 signalling pathway, which also induces the epithelial‐mesenchymal transition (EMT) in various types of cancers." (PMID 32537856, 2020). "The upregulation of gene products associated with migration and invasion (osteopontin, MMP1, vimentin, filamin-A, and β-actin) and gene products for extracellular matrix molecules and their modulators (fibronectin, collagen, ITGBL1, and MXRA5) reflects the invasive nature of this cancer." (PMID 25861239, 2015). "Hence, it is hypothesized that ITGBL1 may modulate COAD progression by affecting the interaction between immune cells and malignant tumor cells." (PMID 39840822, 2025). "We observed that ITGA7 had a direct interaction with ITGBL1 in PPI network, which suggested that they might be coexpressed, and all three genes were upregulated DEGs that regulated cell proliferation, invasion and migration in cancers." (PMID 34409913, 2021). "In the current study, we observed a negative correlation between ITGBL1 protein expression and FBLN2 protein expression in AR‐GC cell lines and GC cancer tissues." (PMID 38332530, 2024).
tumor (23 papers, 2012 to 2025). "Injection of ITGBL1-silenced cells also caused a significant decrease in ITGBL1 protein level in tumor tissues." (PMID 35584452, 2022). "In summary, these findings provided an insight that ITGBL1 served as an important diagnostic and prognostic tumor biomarker and a potential therapeutic target for GC, and hence was worth exploration." (PMID 35596183, 2022). "The exception is NSCLC, in which ITGBL1 is postulated to play an opposite role of tumor suppressor, and its decreased level is associated with worse disease course." (PMID 32961775, 2020). "Previous studies have demonstrated that ITGBL1 is associated with tumor invasion and metastasis." (PMID 40287769, 2025). "In addition, we performed the TISIDB database analysis to explore the association between the ITGBL1 level and number of tumor-infiltrating lymphocytes (TILs)." (PMID 35596183, 2022). "In contrast, ITGBL1+ fibroblasts, which progressively accumulated from precancerous lesions to primary tumors and metastases, expressed ITGBL1, a protein implicated in promoting ECM deposition, stiffness, and tumor cell migration." (PMID 41246350, 2025). "Unsurprisingly, tumors in the sh-ITGBL1 group were smaller in size and lighter in weight compared to the sh-NC group, suggesting ITGBL1 absence repressed tumor growth in vivo." (PMID 39840822, 2025). "Transcriptomically, PRELP+ CAFs exhibit a unique signature defined by extracellular matrix components (e.g., PRELP, COLEC11, ITGBL1) and the activation of pro-tumor pathways such as TGF-β and Wnt signaling." (PMID 41031085, 2025). "The high expression of ITGBL1 in GC can promote tumour metastasis by promoting anoikis resistance, and ultimately affect the survival and prognosis of patients." (PMID 38332530, 2024). "Rongkun Li noted that the upregulated expression of ITGBL1 exhibited a favourable correlation with both the tumour‐node‐metastasis (TNM) stage and the occurrence of distant metastasis in GC patients." (PMID 38332530, 2024). "By activating fibroblasts in remote organs, EVs-transferred integrin beta-like 1 (ITGBL1) facilitates metastatic tumor cell growth by triggering the release of pro-inflammatory cytokines IL-6 and IL-8." (PMID 38741166, 2024). "Another investigation revealed that the primary tumours secrete extracellular vesicles abundant in ITGBL1, which facilitate alterations in the milieu of fibrocytes located in remote organs, ultimately fostering their metastatic progression." (PMID 38332530, 2024). "ECM-related integrin, beta-like 1 (ITGBL1), cadherin 11 (CDH11) and trophinin-associated protein (TROAP) were upregulated, perhaps reflecting a reorganisation of the tumour microenvironment that is permissive of invasion and metastasis." (PMID 38124114, 2023). "Ki67 (the typical proliferation marker), TGF-β1 (the TGF-β/Smad pathway-related factor), and MMP2 (metastasis-related factor) protein expressions in tumor tissues were also decreased by ITGBL1 knockdown." (PMID 35584452, 2022). "Previous studies showed that ITGBL1 was dysregulated in several tumors and acted as either carcinogenic or tumor suppressor." (PMID 35596183, 2022). "In contrast, ITGBL1 functioned as a tumor suppressor in NSCLC, inhibiting cell migration and invasion." (PMID 35596183, 2022). "In this study, we showed that the expression of ITGBL1 in HCC tissues is increased compared to adjacent normal tissues, and ITGBL1 higher expression is correlated with incomplete tumour encapsulation and poorer OS in HCC patients." (PMID 32537856, 2020). "Mice were pretreated with EVs containing different levels of ITGBL1 for 3 weeks, following by intravenous injection of tumor cells as experimental metastasis models." (PMID 32139701, 2020). "In our study, we found that tumor-derived ITGBL1-enriched EVs are directly transferred to lung and liver metastatic niche, and converts fibroblasts and stellate cells to CAFs by binding to TNFAIP3, and activating the NF-κB signaling pathway." (PMID 32139701, 2020).